CRP (C-reactive protein)
Diseases named in the same sentence as CRP in open-access papers (continued):
Sharing a sentence is not in itself a finding about the gene and the disease.
depression (continued). "Analyses of data from the Pittsburgh Healthy Heart Project (N = 263) found a weak bidirectional relationship between CRP and Beck Depression Inventory-II." (PMID 31019266, 2020). "Increased CRP levels in depression is a rather late event and marks a persistent pro-inflammatory state." (PMID 33240126, 2020). "Depression has been associated with increased levels of interleukin-6 (IL-6), tumor necrosis factor-alpha (TNF-α), and C-reactive protein (CRP)." (PMID 32380710, 2020). "MDD: Major depressive disorder; SEM: Standard error of the mean; IL-6: Interleukin-6; CRP: C-reactive protein; Ham-D: Hamilton Depression Rating Scale; N: Number." (PMID 30899619, 2019). "Results showed that abdominal pain, joint pain, depression, and C-reactive protein were the influencing factors of sleep efficiency in patients with IBD-PA." (PMID 31970156, 2019). "Some studies and meta-analyses demonstrated the link between CRP levels and depression, highlighting the key role of inflammation in depression." (PMID 31009477, 2019). "We aimed to establish the prevalence of low-grade inflammation in depression, using different C-reactive protein (CRP) levels, through a systematic literature review and meta-analysis." (PMID 31258105, 2019). "High BMI, high scores on vegetative symptoms of depression, low scores on calmness and a history of childhood adversity were all predictive of increased CRP." (PMID 29764522, 2019). "The “normal weight” group with high hs-CRP levels were 2.46 times more likely to have depression than those with low hs-CRP levels." (PMID 30760746, 2019). "Our results provide fresh evidence that patients with treatment-resistant depression have the most abnormally increased CRP levels compared with both treatment-responsive and currently untreated patients." (PMID 29764522, 2019). "Serum levels of interleukin-6 (IL-6), interleukin-33, C-reactive protein (CRP), tumor necrosis factor-α, and macrophage inflammatory protein-1β were found elevated in people with depression." (PMID 30899619, 2019). "A meta-analysis comprising 58 studies indicated that interleukin (IL)-6 and the acute phase reactant C-reactive protein (CRP) were elevated in major depressive disorder, and to a lesser extent, tumor necrosis factor (TNF)-α." (PMID 30967802, 2019). "About a quarter of patients with depression show evidence of low-grade inflammation, and over half of patients show mildly elevated CRP levels." (PMID 31258105, 2019). "A funnel plot of the 25 studies assessing the prevalence of elevated CRP in depression appeared visually symmetrical." (PMID 31258105, 2019). "We also found that positive changes in TNF-α, IL-6, IL-10 and CRP levels significantly correlated with higher reduction in depression symptoms." (PMID 31375659, 2019). "Studies have found that people with major depression have higher levels of pro-inflammatory cytokines, for example, IL-1, IL-6, and tumor necrosis factor-alpha, and C-reactive protein." (PMID 31214060, 2019). "Zinc has been shown to influence brain-derived neurotrophic factor (BDNF) activities, which were found to be related to depression, and to affect depression by reducing several makers of inflammation, such as C-reactive protein or interleukin-6." (PMID 30781841, 2019). "Increased inflammatory blood markers (e.g., CRP and IL-6) correlated with greater overall symptom severity in patients with depression, in particular with neuro-vegetative symptoms (e.g., sleep, appetite)." (PMID 30116031, 2019). "A meta-analysis found that IL-1β, IL-6, TNF and C-reactive protein (CRP) in peripheral blood are the most reliable biomarkers of inflammation in patients with depression." (PMID 31849598, 2019). "The prevalence of elevated CRP (>1 mg/L) in depression was 58% (95% CI 47–69%), and the meta-analytic odds ratio for elevated CRP in depression compared with controls was 1.47 (95% CI 1.18–1.82)." (PMID 31258105, 2019).
depression (continued). "Inflammation is triggered by the release of inflammatory cytokines such as interleukin (IL)-1β IL-2, IL-6, tumor necrosis factor alpha (TNF-α), and C-reactive protein (CRP), which all have been found to be up-regulated in patients with depression." (PMID 31212946, 2019). "Approximately one in four patients with depression show CRP levels >3 mg/L, a widely used threshold to define low-grade inflammation in the literature." (PMID 31258105, 2019). "Patients with depression frequently exhibit increased levels of C-reactive protein, tumor necrosis factor-alpha, and interleukin-6 (Miller, Maletic & Raison, 2009)." (PMID 31592197, 2019). "It has been reported the mean CRP levels are higher in treatment-resistant compared with treatment-responsive patients with depression." (PMID 31258105, 2019). "However, the sex difference in the association between hs-CRP and depression remains unclear." (PMID 30760746, 2019). "Elevated levels of circulating high-sensitivity C-reactive protein (hs-CRP) have been observed in depression, with the body mass index (BMI) being a major mediator of this association." (PMID 30760746, 2019). "When we performed multiple linear regression analysis using hs-CRP and PHQ-9 score for depression as continuous variables, the association between the two variables remained significant in men (β = 0.067, standard error (SE) = 0.026, P = 0.009)." (PMID 30760746, 2019). "Inflammatory markers such as IL-6 and C-reactive protein (CRP) are consistently found to be elevated in depression, although the size of the effect is relatively small." (PMID 31817800, 2019). "High-sensitivity CRP in peripheral venous blood, body mass index (BMI) and questionnaire assessments of depression, anxiety and childhood trauma were measured." (PMID 29764522, 2019). "Men with high hs-CRP levels showed a statistically higher prevalence of depression compared to men with low hs-CRP levels (8.90% vs. 3.65%, P < 0.0001)." (PMID 30760746, 2019). "Data from the National Health and Nutrition Examination Survey (NHANES 2005–2008) were used to examine the relationship between poor dental health and depression among US adults controlling for markers of inflammation, C-reactive protein (CRP) and adiposity." (PMID 30998794, 2019). "After adjusting for potential confounding covariates, elevated hs-CRP (>3.0 mg/L) increased the prevalence of depression independently in men by nearly twofold." (PMID 30760746, 2019). "Depression, low-grade inflammation measured as hs-CRP, higher triglycerides, male sex, and lower age were independently associated with lower HDL-cholesterol levels." (PMID 30885233, 2019). "Current findings highlight a potential independent role of depression and inflammatory markers, CRP and OPG in specific, in the pathophysiology of dyslipidemia in psychotic disorders." (PMID 29721726, 2019). "Abdominal pain, joint pain, depression, and C-reactive protein were the influencing factors of sleep efficiency." (PMID 31970156, 2019). "Subjects with increased blood CRP levels not only suffered from depression but also evidenced altered hippocampal structures, including 11% reductions in the CA1 area and the thickness of the subiculum." (PMID 31581672, 2019). "A funnel plot of the 30 studies assessing the prevalence of low-grade inflammation (CRP >3 mg/L) in depression visually appeared symmetrical." (PMID 31258105, 2019). "In men, the high hs-CRP group was 1.86 times more likely to have depression after adjusting for covariates (adjusted Odds Ratio (OR): 1.86; 95% Confidence Interval (CI): 1.07–3.25; P = 0.029)." (PMID 30760746, 2019). "Yet several groups point out that the effects of anti-inflammatory or immune-modulatory drugs should be evaluated in the subset of patients with depression showing increased CRP levels, which is often interpreted to reflect inflammation." (PMID 30769887, 2019).
depression (continued). "These kinds of interference are frequently made in studies assessing CRP and IL-6 in relationship to stress or depression and that conclude as to the role of inflammation in these conditions." (PMID 30769887, 2019). "Higher levels of interleukin (IL)-1β, IL-6, tumor necrosis factor (TNF)-α, and C-Reactive Protein (CRP) were reported in patients with depression by many investigators." (PMID 31252530, 2019). "In contrast to our findings, a lower concentration of CRP was reported in men with greater odds of having clinically significant depression, but only in patients with the rs1205 minor AA genotype." (PMID 31788733, 2019). "CRP is an archetypal acute phase protein and IL-6 is a pleotropic proinflammatory cytokine, both of which have been studied extensively in depression and shown to be elevated in acutely unwell patients compared with controls." (PMID 29140226, 2018). "Second, the model from our path analysis clarified that cognitive function among our participants was mainly associated with age, education level, food intake, and oral function, although increased CRP and depression levels were also significant." (PMID 29304177, 2018). "They found that depressed patients with CRP levels less than 1 mg/L prior to treatment initiation experienced significantly greater reduction in depression severity with escitalopram as compared to nortriptyline." (PMID 29329256, 2018). "Controlling for CRP did appear to attenuate the effect of depression as defined by a PHQ-9 cut-off score of ≥10." (PMID 28762106, 2018). "In two studies of infliximab which blocks tumor necrosis factor (TNF)-α in patients with major depression, treatment only benefited participants with CRP above a certain level." (PMID 30766494, 2018). "Although many markers for depression had been identified previously, such as CRP, tumor necrosis factor-α (TNF-α), IL-6, the brain-derived neurotrophic factor (BDNF), and so on, the predictability of a single marker was poor." (PMID 30095631, 2018). "Patients with depression show elevated levels of pro-inflammatory cytokines, acute phase reactants such as C-reactive protein (CRP), chemokines, and cell adhesion molecules." (PMID 30524737, 2018). "There are many markers of the peripheral immune system that can be conveniently measured in venous blood samples from patients with depression, including cytokines, CRP, and other proteins; cell counts from flow cytometry; and gene transcription." (PMID 28688579, 2018). "The acute-phase protein CRP and the proinflammatory cytokine IL-6 are the most frequently investigated biomarkers of inflammation in cross-sectional and prospective studies on depression." (PMID 29520075, 2018). "It is also noteworthy that peripheral levels of IL-6 and CRP differentiate MS patients with depression from those free of depression." (PMID 29294244, 2018). "In a subsample where CRP was available, the results remained similar although only continuous depression symptom scores were predictive of mortality." (PMID 28762106, 2018). "Low-grade inflammation, hereafter also referred to as ‘inflamed depression’, will be defined as serum high-sensitivity CRP (hs-CRP) level ≥3 mg/L." (PMID 30244217, 2018). "A large, population-based study from Denmark reported that about one third of patients with a history of hospitalisation for depression show evidence of low-grade systemic inflammation, defined as a serum CRP level >3 mg/L." (PMID 29544672, 2018). "The pairwise comparisons of IL-6, TNF-α and CRP in patients with different depression degrees in observation group showed statistically significant differences (P<0.05)." (PMID 30181997, 2018). "The results showed that chronic unpredictable mild stress (CUMS) induces depression-like behavior in rats, accompanied by increased plasma concentrations of CRP and IL-6." (PMID 30429764, 2018). "Our results are in line with previous studies reporting prevalence of low-grade inflammation (CRP >3 mg/L) in depression." (PMID 29544672, 2018).
depression (continued). "Depression has therefore been associated with high levels of IL-6, TNF-α, IL-1 beta, C-reactive protein (CRP), chemokines, and adhesion molecules." (PMID 29619128, 2018). "A similar pattern was observed in another study, where the authors found a significant interaction between hostility and depression symptoms for serum IL-6 and CRP." (PMID 29623033, 2018). "Meta-analyses have indicated that C-reactive protein (CRP), interleukin-6 (IL-6), and TNF-α are the most robust evidence-based inflammatory markers associated with depression." (PMID 30429764, 2018). "A prospective community-based study of children (n = 1420) aged 9, 11 and 13 years with follow-up to 21 years examined bi-directional associations between the inflammation biomarker C-reactive protein (CRP) and depression." (PMID 30460320, 2018). "A trial with add-on infliximab (an inhibitor of the inflammatory TNF-alpha) has revealed an increased clinical response compared with antidepressants alone in patients with treatment-resistant depression, but only in those with a CRP of >5 mg/L." (PMID 29615964, 2018). "Assessing depression and oral health condition with the use of a questionnaire examination, O’Neil at al simultaneously controlled the C-reactive protein (CRP)." (PMID 30313038, 2018). "In fact, markers of inflammation, for example, CRP, are also associated with depressive disorders; however, the effects of ECT to acute phase reactants such as CRP and PCT are not well known yet." (PMID 29545905, 2018). "Convergent evidence of higher peripheral IL-1β, IL-6, TNF-α and CRP levels would support the psychoneuroimmunology theory as contributory to depressive syndromes and Alzheimer’s disease in elderly." (PMID 30104698, 2018). "Intima media thickness (IMT), a marker of preclinical atherosclerosis, was recently associated with increased CRP and reduced HRV in patients suffering from depression." (PMID 28376102, 2017). "The authors concluded that there is a positive correlation between depression and the increase of the three inflammatory cytokines: CRP, IL-1 and IL-6." (PMID 26649857, 2017). "There are multiple studies showing elevated high sensitivity- (hs-) C-reactive protein (CRP) levels in blood samples from patients with psychiatric disorders (schizophrenia, depression, PTSD, anxiety, and autism)." (PMID 29181395, 2017). "CRP meta-analysis have identified this protein's link with depression, though this remains a contentious result." (PMID 27555379, 2017). "Multiple linear regression analyses were used to evaluate the cross-sectional and longitudinal relationship between depression and baseline hs-CRP." (PMID 28128231, 2017). "Individuals with increased plasma levels of C-reactive protein (CRP), an acute phase marker of inflammation, are at greater risk for the development of depression, and increased plasma level of CRP in adolescents is predictive of addiction later in life." (PMID 28210782, 2017). "Our main findings are that patients with later onset of depression exhibit higher levels of two inflammatory markers (i.e., CRP, NLR) and lower levels of cytotoxic T cells after adjusting for sociodemographics, lifestyle factors, and antidepressant medication." (PMID 29218020, 2017). "Patients with major depression also often show increased inflammatory markers, including C-reactive protein (CRP), interleukin-6 (IL-6), and tumor necrosis factor (TNF)-α, relative to controls." (PMID 28670290, 2017). "Increased expression of pro-inflammatory cytokines IL-1β, IL-6, TNF-α, as well as interferon gamma (IFN-γ), and C-reactive protein (CRP) is repeatedly observed in patients suffering from depression and has been associated with specific symptoms of depression." (PMID 28239408, 2017). "The present study aimed to investigate the role of abnormal body mass index (BMI, kg/m2) in the depression-CRP (C-reactive protein) relationship in a healthy middle-aged and elderly Chinese population." (PMID 28128231, 2017).
depression (continued). "In one study, CRP levels was measured before and after treatment, while we concluded that antidepressant drugs, not only treated depression, but also reduced inflammatory markers." (PMID 28487875, 2017). "A total of 2068 participants were free of depressive symptoms (less than four of eight symptoms) in 2004/05 and 2008/09 and also had data on CRP on those same occasions, had follow-up data on depression status in 2012/13, and had data on covariates in 2008/09." (PMID 28809860, 2017). "Previous reports have shown that CRP is significantly elevated with depression, particularly in men and the results of this study agree with these findings." (PMID 29190710, 2017). "It was suggested in several studies that release of several cytokines such as tumour necrosis factor and C-reactive protein, as well as the effects of depression and distress were the mechanisms of sleep disorders." (PMID 29379668, 2017). "A recent meta-analysis showed raised inflammatory markers such as IL-6 or C-reactive protein (CRP) are significantly associated with the subsequent development of depressive symptoms, which supports the hypothesis that there is an association between the inflammation and depression." (PMID 30886949, 2017). "Questionnaires on depression and physical activity and a fasting blood sample for C-reactive protein and the Omega-3 Index were also collected." (PMID 29291133, 2017). "In subjects exposed to higher levels of childhood life events, the transition to depression was accompanied by increases in CRP and IL-6." (PMID 28463238, 2017). "Longitudinal analyses of observational data provide inconsistent information on the temporal order between CRP, proinflammatory cytokines and depression." (PMID 26631274, 2016). "Those with inflammation indicated by high C-reactive protein (CRP) had more depression and bipolar disorder and more than twice the suicide rate of those with low CRP111–113." (PMID 27303633, 2016). "The authors assessed IL-6 and CRP at baseline and depressive symptoms using the Center for Epidemiological Studies—Depression (CES-D) scale." (PMID 27918465, 2016). "Abdominal adipose tissue produces inflammatory cytokines, including C-reactive protein (CRP), and hormones that contribute to immuno-metabolic responses associated with metabolic disease and depression." (PMID 27227974, 2016). "Levels of CRP, soluble E selectin, CD40 ligand, interleukin-6, tumor necrosis factor alpha, and high sensitivity CRP are deregulated in patients diagnosed with major depressive disorder." (PMID 27176617, 2016). "The association between elevated CRP and male MDD confirms the findings of a previous NESDA and other large cohort studies, including a meta-analysis of CRP in depression." (PMID 27232630, 2016). "Our findings are consistent with previous MR studies reporting null associations of genetically elevated CRP levels with inflammation-related outcomes including CAD, type 2 diabetes, high body mass index, Alzheimer disease, and depression." (PMID 27327646, 2016). "Severe depression was more strongly associated with IL-6, CRP and TNF-α compared to moderate depression." (PMID 26065825, 2015). "A randomized controlled trial revealed that antidepressant treatment with the selective serotonin reuptake inhibitor (SSRI), sertraline, significantly decreased not only depression scores, but also baseline measurements of CRP and IL-6 in depressed subjects." (PMID 26550011, 2015). "C-reactive protein (CRP), interleukin–6 (IL–6), and tumor necrosis factor alpha (TNF-α) have previously been shown to associate with LUTS, depression and anxiety, while myeloperoxidase (MPO) has also been linked to the development of depression." (PMID 26445118, 2015). "A linear regression model was fitted to further explore cross-sectional associations between CRP levels and FAS scores, by including depression scores, anxiety scores, and daily step counts at each assessment as covariates." (PMID 26599129, 2015).